GK (glycerol kinase)
Diseases named in the same sentence as GK in open-access papers (continued):
Sharing a sentence is not in itself a finding about the gene and the disease.
steatosis (3 papers, 2014 to 2024). Increased lipid within the cytoplasm of cells. "FABP1 plays a key role in the uptake and transport of fatty acid and in steatosis development, while GK is directly involved in TG synthesis." (PMID 36770927, 2023). "Additionally, a comparison between drugs causing phospholipidosis and/or steatosis revealed 26 genes to be regulated in common including 4 signature genes to predict DIS (PKLR, GK, FABP7 and FADS1)." (PMID 25470483, 2014). "In detail, we found the down expression of FABP1 (40 times) and APOC3 (11.98 times), PPARGC1A and GK (11 times), ABCA1 and SRBF2 (3 times) compared to the steatosis control." (PMID 36770927, 2023). "Furthermore, a comparison between drugs inducing phospholipidosis and/or steatosis uncovered 26 commonly regulated genes, including from the signature markers (PKLR, GK, FABP7 and FADS1)." (PMID 38791241, 2024). "In our experiments, the downregulation of genes involved in lipid/cholesterol metabolism and transport (such as FABP1, APOC3, PPARGC1A, GK, ABCA1, and SRBF2) induced by curcumin treatment could explain the observed reduction of steatosis and lipid content." (PMID 36770927, 2023). "The treatment with curcumin-andrographolide in association maintained the ability to regulate in a negative manner FABP1 (15.96 times), PPARGC1A (7.85 times), GK and ABCA1 (4 times), and APOC3 (2.04 times) in respect to the steatosis control." (PMID 36770927, 2023).
adrenal hypoplasia (2 papers, 2019 to 2021). "Gk isexpressed in various organs, and deficiency of GK causes an X-linked recessive disease in humans, which shows hyperglycerolemia associated withcongenital adrenal hypoplasia and developmental delay." (PMID 30662012, 2019).
breast carcinoma (2 papers, 2022 to 2024). "Overall, the induction of OS, dysfunction, and uncoupling of the mitochondria and the reduction of autophagy could be molecular mechanisms that underlie the reduction of the 4T1 breast cancer induced by GK-1." (PMID 36670920, 2022). "The results revealed that GK expression was notably upregulated in several cancers, including breast cancer, esophageal squamous cell carcinoma (ESCA), and gastric cancer, while it was significantly downregulated in others, such as colon cancer, lung squamous cell carcinoma, and thyroid carcinoma." (PMID 38365953, 2024).
developmental delay (2 papers, 2008 to 2019). "We report a girl with a de novo deletion at Xp21.2 on the maternal chromosome, including DAX1, the GK gene and 3′ end of the dystrophin gene, who presented with salt losing adrenal insufficiency and moderate developmental delay, but relatively mild features of muscular dystrophy." (PMID 18762570, 2008).
esophageal carcinoma (2 papers, 2024). A primary or metastatic malignant neoplasm involving the esophagus. "However, the role of Glycerol Kinase (GK), a key enzyme in glycerol metabolism, in Esophageal Carcinoma (ESCA) remains unclear." (PMID 38365953, 2024). "In addition, GK has been proposed to be a prognostic predictor in esophageal carcinoma (ESCA) based on a Kaplan–Meier survival analysis of Cancer Genome Atlas (TCGA) data, which indicated that elevated GK expression is associated with poorer outcomes in ESCA patients." (PMID 39199385, 2024).
liver cancer (2 papers, 2024). An epithelial or non-epithelial malignant neoplasm that arises from the liver. "An analysis of human liver cancer samples from the TCGA, using KM survival plots, suggests that low GK and GPDH expressions are associated with reduced overall survival." (PMID 38365953, 2024). "This decrease in GK protein within preneoplastic lesions suggests that glycerol uptake and metabolism in the early stages of liver cancer development are predominantly functions of the surrounding tissue, not the lesion itself." (PMID 38365953, 2024). "In the context of liver cancer, changes in GK activity can be detected at the disease's early stages and continue throughout its advancement, which suggests that the GK gene is a potential therapeutic target in developing treatments for HCC." (PMID 38693536, 2024).
Sepsis (2 papers, 2019 to 2024). Sepsis is defined as life-threatening organ dysfunction caused by a dysregulated host response to infection. "The Venn diagram shows that a total of eight overlapping genes were discovered between ACSL4 co-expression genes and sepsis, including GK, CLEC4E, ACSL1, TGFBR3, ADAM9, AZI2, BCAT1, and CYP1B1." (PMID 39262873, 2024). "The qPCR results suggest that GK and PFKFB3 might contribute to the progression of S. aureus-induced sepsis, and CEACAM1, TNFAIP6, PSTPIP2, SOCS3, and IL18RAP might be closely linked with E. coli-induced sepsis." (PMID 31093495, 2019). "The qPCR results suggested that GK and PFKFB3 might contribute to the progression of S. aureus-induced sepsis, and GK, CEACAM1, TNFAIP6, PSTPIP2, SOCS3, and IL18RAP might be closely linked with E. coli-induced sepsis." (PMID 31093495, 2019).
tuberculosis (2 papers, 2019 to 2025). A chronic, recurrent infection caused by the bacterium Mycobacterium tuberculosis. "Collectively, these multi-tiered validation data robustly support the involvement of ASPHD2, GCH1, and GK in tuberculosis pathogenesis and immune activation, highlighting their potential as protein-level biomarkers for the assessment of treatment response." (PMID 40808944, 2025). "Future studies will aim to enlarge the sample pool to encompass tuberculosis (TB) patients and healthy controls from a broader array of geographic regions and ethnic backgrounds, thereby enabling a more comprehensive validation of the involvement of ASPHD2, GK, and GCH1 in the pathogenesis of TB." (PMID 40808944, 2025).
X-linked AHC (2 papers, 2022 to 2023). "Xp21 deletion usually contains DAX1 (resulting in X-linked AHC), GK (resulting in glycerol kinase deficiency), and DMD deletion (resulting in Duchenne muscular dystrophy)." (PMID 37237297, 2023). "This suggests that most of the contiguous gene deletions in patients with DAX1-related X-linked AHC contain DAX1, GK, and DMD deletions." (PMID 37237297, 2023).
adrenocortical insufficiency (1 paper, 2016). An endocrine or hormonal disorder that occurs when the adrenal cortex does not produce enough of the hormone cortisol and in some cases, the hormone aldosterone. "Contiguous gene deletions of chromosome Xp21 can lead to glycerol kinase deficiency and severe adrenocortical insufficiency (AI) in a male newborn among other problems." (PMID 27087023, 2016).
atherosclerosis (1 paper, 2022). A disease characterized by the build-up of fatty material and calcium deposition in the arterial wall resulting in partial or complete occlusion of the arterial lumen. "Many studies have shown that GK is an essential enzyme in the formation of triacylgycerol, which contributes to the development and progression of atherosclerosis." (PMID 36187340, 2022). "Overexpression of CXCL3, GK, FPR1, and LST1 was advanced recognition and intervention factors for unstable plaques, which might become targets for atherosclerosis rupture prevention." (PMID 36187340, 2022).
Autoimmunity (1 paper, 2022). The occurrence of an immune reaction against the organism's own cells or tissues. "Neoepitopes derived from citrullination modification of islet proteins, citrullinated GK and/or other unknown glucose-insulin metabolic proteins, compromises immune tolerance to trigger T and B cell autoimmunity." (PMID 35388005, 2022). "In addition, as a biomarker of autoimmunity, inflammation-induced citrullination of GK alters its metabolic functions of glucose sensing in pancreatic beta cells." (PMID 35388005, 2022).
Crohn disease (1 paper, 2020). A gastrointestinal disorder characterized by chronic inflammation involving all layers of the intestinal wall, noncaseating granulomas affecting the intestinal wall and regional lymph nodes, and transmural fibrosis. "Examination of human samples have further confirmed that the reduction of GK expression in the small bowel is associated with colonic involvement in human Crohn’s disease." (PMID 31941439, 2020).
dentin caries (1 paper, 2018). "Other taxa that glycerol kinase genes mapped to in dentin caries included: Rothia aeria (DC 3.4, CC 1.6, CF 0.4), P. denticola (DC 2.4) R. dentocariosa (DC 2.1, CC 1.5, CF 0.1) and S. australis (DC 1.1, CC 0.1)." (PMID 30034639, 2018). "The highest gene expression was in dentin caries including for ADS, glycerol kinase, uracil-DNA glycosylase and urease." (PMID 30034639, 2018). "Glycerol kinase is part of the glycolysis pathway rather than that for refined carbohydrates as reported for dentin caries." (PMID 30034639, 2018).
diabetic foot ulcers (1 paper, 2025). "To comprehensively understand the role of the cuproptosis-associated gene GK in reshaping cell communication within the diabetic foot ulcer (DFU) microenvironment, we analyzed cell–cell interactions using CellChat analysis." (PMID 41583446, 2025). "However, through subsequent bioinformatics analyses, including differential gene expression and immune cell interaction studies, GK emerged as a key gene associated with the immune microenvironment in diabetic foot ulcers (DFUs)." (PMID 41583446, 2025). "In summary, our study identifies GK and cuproptosis-related signaling as promising new leads in the quest to understand and ultimately break the cycle of chronic inflammation in diabetic foot ulcers." (PMID 41583446, 2025).
E. coli infection (1 paper, 2019). "As for the eight common genes screened out in all four datasets, CEACAM1, GK, PFKFB3, and TNFAIP6 emerged repeatedly in the S. aureus group, but CEACAM1, IL18RAP, LILRA5, PFKFB3, PSTPIP2, and SOCS3 emerged in the E. coli infection." (PMID 31093495, 2019).
esophageal adenocarcinoma (1 paper, 2024). A malignant tumor with glandular differentiation arising predominantly from Barrett mucosa in the lower third of the esophagus. "In this study, we present pioneering evidence linking high Glycerol Kinase (GK) expression to the incidence of Esophageal Squamous Cell Carcinoma (ESCA), encompassing both Esophageal Adenocarcinoma (EA) and ESCC." (PMID 38365953, 2024).
gestational diabetes (1 paper, 2020). Carbohydrate intolerance first diagnosed during pregnancy. "We present a case of a novel missense mutation in the GK gene leading to isolated glycerol kinase deficiency and pseudohypertriglyceridemia in a male infant of a mother with gestational diabetes." (PMID 32832184, 2020). "Additionally, a potential maternal-fetal interaction between gestational diabetes and glycerol kinase deficiency is discussed." (PMID 32832184, 2020).
glomerulosclerosis (1 paper, 2008). A hardening of the kidney glomerulus caused by scarring of the blood vessels. "For example glomerulosclerosis in congenic rats may either develop as a consequence of permanent hyperglycaemia and hyperinsulinaemia or originate from the effect of specific GK variants." (PMID 18698428, 2008).
Glucocorticoid deficiency (1 paper, 2016). "Glucocorticoid deficiency was observed only in one (0.4%) patient with glycerol kinase deficiency." (PMID 27086477, 2016). "Glucocorticoid deficiency was detected in only 1 of 248 (0.4%) patients whose serum ACTH and cortisol levels were measured, and the diagnosis was glycerol kinase deficiency." (PMID 27086477, 2016).
Hypercholesterolemia (1 paper, 2023). An increased concentration of cholesterol in the blood. "In rat models of hypercholesterolemia, rats receiving chickpeas re-established the liver glycogen deposition compared to the control group; this effect has been correlated to the increase in GK activity." (PMID 37727633, 2023).
Hyperinsulinemia (1 paper, 2022). An increased concentration of insulin in the blood. "In several studies, increased GK activity was found in obese diabetic patients and obese Zucker rats with hyperinsulinemia." (PMID 35893906, 2022).
Hypoglycemia (1 paper, 2025). A decreased concentration of glucose in the blood. "Disruption of the GK gene can produce different phenotypes, ranging from asymptomatic hyperglycerolaemia and pseudohypertriglyceridemia, as this case presents, to a severe metabolic crisis with vomiting, hypoglycemia, loss of consciousness, and seizures during episodes of increased catabolism." (PMID 41583306, 2025).
isovaleric acidemia (1 paper, 2017). "Individual gene performances (using RWR) for this sign varied from best prediction (rank = 1) for IVD (isovaleryl-CoA dehydrogenase) causing isovaleric acidemia, to worst (rank = 7525) for GK (glycerol kinase) causing glycerol kinase deficiency." (PMID 28715999, 2017).
latent infection (1 paper, 2022). "Based on our current and previous studies, we conclude that the interaction of gK with SPP regulates both primary and latent infection in a tissue-dependent manner." (PMID 36215312, 2022).
lymph node metastasis (1 paper, 2024). "Subgroup analysis revealed that high GK gene expression in patients with lymph node metastasis and those with a high BMI indicated a worse prognosis." (PMID 38365953, 2024).
malaria (1 paper, 2009). Malaria is a serious and sometimes fatal disease caused by a parasite that commonly infects a certain type of mosquito which feeds on humans. "In contrast to P. falciparum, the GK gene from the rodent malaria parasite P. berghei is refractory to deletion (C. Janse, A. Waters, Leiden, Netherlands; D.A.B., unpubl." (PMID 19040641, 2009). "Here we have characterized P. falciparum GK activity both in vivo and in vitro and present evidence that blood stage malaria parasites (asexual or sexual) do not utilize host-derived glycerol." (PMID 19040641, 2009).
male infertility (1 paper, 2026). The inability of the male to effect fertilization of an ovum after a specified period of unprotected intercourse. "Glycerol itself and/or via its metabolism by GK or the glycerol shunt, and Gro3P as well, play a key role in sperm health and male fertility, as any dysregulation of glycerol and Gro3P metabolism causes disturbed sperm function and male infertility via mechanisms that need to be understood." (PMID 40927981, 2026). "Neither GK2 nor GKl1 has glycerol kinase activity in vitro; however, their deficiency in mice causes disordered mitochondrial sheath formation in sperm and male infertility." (PMID 40927981, 2026).
neonatal diabetes mellitus (1 paper, 2021). Neonatal diabetes mellitus presents as hyperglycemia, failure to thrive and, in some cases, dehydration and ketoacidosis which may be severe with coma, in a child within the first months of life. "Thus, activity-diminishing GK variants cause MODY2 or permanent neonatal diabetes mellitus (PNDM), whereas activating GK variants result in congenital hyperinsulinism (CHI)." (PMID 34532767, 2021).
nonalcoholic fatty liver (1 paper, 2024). "This work found that glycerol kinase (GK) is upregulated in diet‐induced and genetic mouse models of nonalcoholic fatty liver (NAFL)." (PMID 39418169, 2024). "Whether GK contributes to nonalcoholic fatty liver (NAFL) is unclear." (PMID 39418169, 2024).
parasitic diseases (1 paper, 2024). "Relatively few glycerol analogues have previously been explored for their use as glycerol kinase inhibitors, in addition to their therapeutic potential, however their use as (pro)‐drugs in the context of parasitic diseases such as trypanosomiasis is unreported." (PMID 39263751, 2024).
periodontitis (1 paper, 2024). An acute or chronic inflammatory process that affects the tissues that surround and support the teeth. "Glycerol-3-phosphate, which is the product of glycerol phosphorylation by glycerol kinase, is elevated both in periodontitis and OSCC." (PMID 38786754, 2024).
prostate carcinoma (1 paper, 2024). A carcinoma that arises from epithelial cells of the prostate gland. "It is unclear why GK is differently expressed in a subset of prostate cancer cells, though it is conceivable that GK may implicated in the regulation of sex hormones in prostate cancer." (PMID 39199385, 2024). "Prior to investigating the novel role of GK in prostate cancer, we constructed a recombinant human GK plasmid to be expressed in mammalian cells." (PMID 39199385, 2024). "Nevertheless, the function of GK in cancer remains incompletely understood, which is presumably due to limited research on GK, GK subtypes, and the relationship between GK and prostate cancer." (PMID 39199385, 2024). "This study proposes that GK may have a novel function in prostate cancer, and it investigates the impacts of exogenously transfected human GK on prostate cancer cells." (PMID 39199385, 2024). "To explore this hypothesis, we transfected a GK expression plasmid into human prostate cancer PC-3 cells, which express GK at low levels." (PMID 39199385, 2024). "In other words, GK overexpression could potentially lead to excessive carbon consumption and glucolipotoxicity in prostate cancer, disrupting intracellular energy balance and eventually triggering apoptosis." (PMID 39199385, 2024). "Interestingly, our DNA microarray analysis confirmed a significant increase in the gene expression of GK in prostate cancer PC-3 cells treated with several anti-cancer agents, suggesting the involvement of the GK gene in cancer cell death." (PMID 39199385, 2024). "Consequently, it can be speculated that GK overexpression leads to excessive carbon consumption and nutrient overload, which may potentially induce apoptosis in prostate cancer cells." (PMID 39199385, 2024). "Furthermore, RNA and protein production assays, GK activity analysis, subcellular fractionation, cell viability assays, and apoptosis analysis were executed to determine whether GK has anti-tumor activity in prostate cancer cells." (PMID 39199385, 2024).
sleeping sickness (1 paper, 2023). "So far, this reverse activity has only been reported for GK from Trypanosoma brucei, a group of parasites which cause sleeping sickness and nagana in sub-Saharan Africa15,41." (PMID 37669981, 2023).
vaginal infection (1 paper, 2013). "The gK-null virus vaccine efficiently protected mice against lethal vaginal infection with either HSV-1(McKrae) or HSV-2 (G)." (PMID 24165088, 2013).